PRAMEF5 (PRAME family member 5)
Synonyms: PRAMEF23; PRAMEF5L
Tractability: No criterion of Open Targets' tractability assessment is met for any kind of drug.
Gene: Protein-coding gene on chromosome 1 (13,254,198 to 13,263,435, forward strand). Ensembl gene ENSG00000270601.
Gene Ontology:
Molecular function: ubiquitin-like ligase-substrate adaptor activity
Biological process: proteasome-mediated ubiquitin-dependent protein catabolic process; negative regulation of apoptotic process; negative regulation of cell differentiation; negative regulation of DNA-templated transcription; positive regulation of cell population proliferation
Cellular component: Cul2-RING ubiquitin ligase complex; cytoplasm
Genetic constraint (gnomAD): Loss-of-function variants: 3 observed, 4.75 expected, observed/expected ratio (o/e) 0.63, 90% interval 0.28 to 1.55. That is too few expected variants to judge how well the gene tolerates losing a copy. Missense variants: 20 observed, 40.91 expected, observed/expected ratio (o/e) 0.49, 90% interval 0.34 to 0.71. Synonymous variants: 9 observed, 14.73 expected, observed/expected ratio (o/e) 0.61, 90% interval 0.37 to 1.07.
Homologues: Orthologues: mouse Pramel13 (46% identical), rat Pramef12 (45% identical), rat Pramef8 (44% identical), mouse Pramel12 (44% identical), mouse Pramel15 (43% identical), rat Pramef20 (43% identical), rat Pramef20l1 (43% identical), rat Pramef5 (43% identical), rat Pramel36l1 (43% identical), mouse Pramel16 (42% identical), mouse Pramel31 (42% identical), rat LOC120103107 (42% identical), and 78 more. Paralogues in human: PRAMEF6 (99% identical), PRAMEF15 (98% identical), PRAMEF25 (97% identical), PRAMEF26 (97% identical), PRAMEF9 (97% identical), PRAMEF27 (96% identical), PRAMEF4 (96% identical), PRAMEF11 (96% identical), PRAMEF20 (82% identical), PRAMEF12 (63% identical), PRAMEF8 (63% identical), PRAMEF7 (62% identical), and 12 more.